MYO5C (myosin VC)
Description:
May be involved in transferrin trafficking. Likely to power actin-based membrane trafficking in many physiologically crucial tissues.
Synonyms: MGC74969
Tractability: Small molecule: a structure with a bound ligand is known. PROTAC: ubiquitination databases record sites on it; its protein half-life has been measured.
Gene: Protein-coding gene on chromosome 15 (52,192,309 to 52,295,815, reverse strand). Ensembl gene ENSG00000128833.
Subcellular location (Human Protein Atlas): Cytosol; Nucleoplasm
Gene Ontology:
Molecular function: actin filament binding; ATP binding; cytoskeletal motor activity
Biological process: endocytosis
Cellular component: cytosol; extracellular exosome; nucleoplasm; actin cytoskeleton; myosin complex
Genetic constraint (gnomAD): Loss-of-function variants: 144 observed, 185.13 expected, observed/expected ratio (o/e) 0.78, 90% interval 0.68 to 0.89. The upper end of that interval is the gene's LOEUF score, 0.89, which puts it in group 3 of 6, group 1 being the genes least tolerant of losing a copy. Missense variants: 1,756 observed, 1,900.8 expected, observed/expected ratio (o/e) 0.92, 90% interval 0.89 to 0.96. Synonymous variants: 622 observed, 686.47 expected, observed/expected ratio (o/e) 0.91, 90% interval 0.85 to 0.97.
Homologues: Orthologues: chimpanzee MYO5C (99% identical), macaque MYO5C (97% identical), pig MYO5C (94% identical), dog MYO5C (93% identical), rabbit MYO5C (92% identical), rat Myo5c (90% identical), mouse Myo5c (89% identical), guinea pig MYO5C (82% identical), tropical clawed frog myo5c (71% identical), zebrafish myo5c (64% identical). Paralogues in human: MYO5A (55% identical), MYO5B (51% identical), MYH6 (26% identical), MYH3 (26% identical), MYH2 (26% identical), MYH4 (26% identical), MYH7 (26% identical), MYH7B (26% identical), MYH1 (26% identical), MYH8 (26% identical), MYH10 (26% identical), MYH13 (26% identical), and 32 more.
Diseases named in the same sentence as MYO5C in open-access papers:
MYO5C is named in the same sentence as 11 diseases in open-access papers, as found by Europe PMC text mining. Sharing a sentence is not in itself a finding about the gene and the disease. The quoted sentences say what the papers report.
cancer (2 papers, 2022 to 2023). A tumor composed of atypical neoplastic, often pleomorphic cells that invade other tissues. "Consistent with previous reports about the elevated expression in other cancers, MYO1B, MYO5A, and MYO10 levels were increased in HNSCC tissues compared with adjacent normal tissues whereas MYO5C expression was found to be downregulated." (PMID 35478939, 2022).
tumor (2 papers, 2012 to 2022). "In this model, MYO5C was not linked with proliferation, as observed in tumor expression data, but with differentiation (increased expression in the differentiating medium but not in the control medium)." (PMID 22724020, 2012). "Furthermore, the protein levels of MYO1B, MYO5A, MYO5C, and MYO10 in HNSCC tumor tissues and normal tissues were examined by Human Protein Atlas (HPA) database; consistently, the protein levels of MYO1B and MYO10 were dramatically enhanced in tumor tissues compared with normal tissues." (PMID 35478939, 2022).
MYO5C also shares sentences with these, for which no sentence is quoted: adenoma (1 paper); asthma (1); bladder cancer (1); cardiac arrhythmia (1); iron deficiency (1); non-small cell lung carcinoma (1); Obesity (1); rheumatoid arthritis (1); type 2 diabetes mellitus (1).